TRAF4 (TNF receptor associated factor 4)
Diseases named in the same sentence as TRAF4 in open-access papers (continued):
Sharing a sentence is not in itself a finding about the gene and the disease.
tumor (continued). "Tumor necrosis factor receptor associated factor 4 (TRAF4) is a RING domain E3 ubiquitin ligase that mediates the ubiquitination of various proteins and plays an important role in driving tumor progression." (PMID 35692762, 2022). "Previous studies have confirmed that TRAF4 promoting tumor proliferation, migration, invasion through various pathways, but the mechanism by which TRAF4 inhibits apoptosis is not yet clear." (PMID 35692762, 2022). "Silencing HCG18 reduced tumour size and levels of Ki67 and TRAF4/5 while increasing miR-29a/b levels in vivo." (PMID 34983361, 2022). "TRAF4 is overexpressed in many tumors notably, and because of its important ubiquitination function, it is involved in key signaling pathways in tumor progression." (PMID 36077559, 2022). "SMURF2, a significant partner for TRAF4, exhibits multifaceted functions serving as both tumor promoter and suppressor and is involved in apoptosis, metastasis, senescence, and genomic stability." (PMID 35864174, 2022). "What role TRAF4 plays in tumor immune evasion requires further exploration by subsequent researchers." (PMID 36077559, 2022). "The current study demonstrated that TRAF4 was overexpressed in OSCC tumor tissues and exhibited higher expression in the relapsed tumor specimens after IR treatment." (PMID 36535926, 2022). "The relationship between EGFR/TRAF4 signaling and tumor proliferation was established based on experiments with tumor cell lines." (PMID 35748027, 2022). "To explore the role of TRAF4 involved in tumorigenesis, we analyzed the expression of TRAF4 in tumor and adjacent tissues in the GEPIA database." (PMID 36077559, 2022). "Considering our data in EOC cells, HCG18 and TRAF4 are potential regulators of the tumour microenvironment in EOC." (PMID 34983361, 2022). "There is increasing evidence that TRAF4, as an E3 ubiquitin ligase, is involved in the growth, proliferation, and metastasis of tumor cells." (PMID 36077559, 2022). "TRAF4 promotes the epithelial-mesenchymal transition of non-small cell lung cancer and enhances the proliferation and invasion of tumor cells." (PMID 35692762, 2022). "TRAF4 is involved in various important signal transduction in cells and it plays important functions in the immune system, nervous system, tumor growth and metastasis, cell differentiation, and DNA damage response." (PMID 36077559, 2022). "By the growth rate, Traf4−/− tumor cells had a significantly decreased level of Ki67 and reduced mRNA expression of Cyclin D and C‐myc." (PMID 35748027, 2022). "Consistent with the data from GEPIA, TRAF4 was expressed at higher levels in GBM than that in non-tumor tissues." (PMID 36077559, 2022). "The overexpression of activated AKT reverses cell growth arrest in TRAF4-silenced cells, which plays an essential role in breast carcinogenesis by activating and interacting with AKT." (PMID 35242717, 2022). "Of the 42 patients with ≥ twofold increase in TRAF4 expression, 32 (76.2%) had local tumor recurrence within 24 months after dCRT." (PMID 34488754, 2021). "Other chemotherapeutic agents, such as oxaliplatin and irinotecan, also inhibited TRAF4-knockout tumor development from HT29 cells." (PMID 32357935, 2020). "TCGA database showed that TRAF4 expression was significantly upregulated in tumor tissues, especially in CESC." (PMID 32087604, 2020). "In vivo experiments also showed that the lncRNA SNHG15 knockdown promotes the OS tumor growth through sponging miR-346 to allow TRAF4 expression." (PMID 33817231, 2020). "Then TRAF4 overexpression offset the suppressing effects of ZFPM2-AS1 depletion on tumor size, volume and weight." (PMID 32280300, 2020).
tumor (continued). "The FCM, EdU, and MTS assay results demonstrated that miR-29s dramatically suppressed G1/S-phase transition and tumor cell proliferation, while ectopic TRAF4 efficaciously compromised these effects (P < 0.05–0.001)." (PMID 30348972, 2018). "Accordingly, the increase in the TRAF4 level was positively associated with the wild-type IDH1/2 gene, older age, advanced tumor grade, and higher Ki-67 LI (P < 0.0001)." (PMID 30348972, 2018). "In the DMBA/TPA-induced skin cancer model, TRAF4−/− mice exhibit remarkably reduced tumor incidence and tumor numbers." (PMID 30294322, 2018). "On the other hand, we found the expression of TNF-α, TRAF2 and TRAF4 was enhanced in the primary tumor as time goes on." (PMID 28774312, 2017). "Based on our results, we suggest that the TRAF4/NOX complex is a key regulator involved in alteration of the tumor microenvironment in normal lung fibroblasts." (PMID 28827764, 2017). "To confirm the involvement of TRAF4 in modulation of the tumor microenvironment, we established an in vivo xenograft mouse model." (PMID 28827764, 2017). "In this study, we suggest that post-translational modification of TRAF4 plays a role in allowing fibroblasts to establish a tumor progressive microenvironment." (PMID 28827764, 2017). "Taken together, these findings indicate that TRAF4 in fibroblasts plays a crucial role in modulation of the tumor microenvironment through up-regulation of sICAM1, leading to stimulation of nearby tumor cell proliferation and EMT." (PMID 28827764, 2017). "To widen the comprehension of normal fibroblasts as CAFs, we focused on the role of TRAF4 in modulating the tumor microenvironment in normal lung fibroblasts." (PMID 28827764, 2017). "Overexpression of TRAF4 induces apoptosis and suppresses colony formation in multiple tumour cell lines suggesting a role for TRAF4 in determining cell fate in response to stabilization of p5336." (PMID 27581768, 2016). "Here, we uncovered a robust clinical correlation between nuclear TRAF4 and tumor grades." (PMID 39716976, 2025). "In our study, we found that OA could specially bind to TRAF4 and OA‐mediated inhibition of tumor sphere formation is dependent on TRAF4 expression." (PMID 39716976, 2025). "Notably, we observed a positive correlation between nuclear TRAF4 levels and tumor grades, suggesting that the translocation of TRAF4 into the nucleus plays a critical role in tumor aggressiveness and differentiation status." (PMID 39716976, 2025). "Our results demonstrated that the AKT inhibitor could effectively suppress TRAF4 nuclear translocation in tumor cells." (PMID 39716976, 2025). "Importantly, pharmacological modulation of TRAF4 nuclear translocation is found to suppress tumor tumorigenicity and metastasis in tumor models." (PMID 39716976, 2025). "Consequently, nuclear TRAF4 promoted the stemness and dormancy of tumor cells, thus assisting in the seeding of tumor cells in livers." (PMID 39716976, 2025). "Two different sgRNAs effectively eliminated endogenous TRAF4 expression in these tumor cells." (PMID 39716976, 2025). "Notably, reduced nuclear TRAF4 led to decreased stemness properties and metastatic dormancy of tumor cells." (PMID 39716976, 2025). "Moreover, reducing TRAF4 nuclear translocation diminished the tumor sphere formation induced by TRAF4, which was restored by recombinant IL‐8." (PMID 39716976, 2025). "Based on this result, we hypothesized that IL‐8 was the principal downstream gene of nuclear TRAF4 that mediates its role in tumor stemness and dormancy." (PMID 39716976, 2025). "Similarly, reducing TRAF4 nuclear translocation suppressed tumor cell invasion that was elevated by TRAF4, which was again restored by recombinant IL‐8." (PMID 39716976, 2025). "In addition, the tumor-bearing mice with TRAF4-depleted NPC cells have a more extended survival period." (PMID 38164179, 2024).
tumor (continued). "Moreover, the tumor mass and tumor weight of TRAF4-depleted CNE2 tumors after IR treatment were prominently reduced consistently." (PMID 38164179, 2024). "The present study found that TRAF4 was significantly increased in CRC clinical tumor samples." (PMID 36765039, 2023). "Compared with that of tumors derived from TRAF4-knockout cells that were not exposed to irradiation or with tumors with TRAF4 WT restored and treated with irradiation, tumor growth was significantly inhibited in xenograft tumors from TRAF4-knockout cells subjected to irradiation." (PMID 36765039, 2023). "Tumor tissues were subjected to western blotting to confirm TRAF4 protein levels." (PMID 35748027, 2022). "Thus, by summarising, we can clearly elucidate that TRAF4 affects the physiological and pathological functions of tumor cells in appealing tumors by participating in signaling pathways." (PMID 35242717, 2022). "Interestingly, TRAF4 and MCL-1 levels exhibited significantly higher levels in relapsed tumor tissues than in primary tumor tissues, and the positive correlation between TRAF4 and MCL-1 was also observed in the relapsed tumors." (PMID 36535926, 2022). "In T-ALL, TRAF4 acts as an inhibitor of apoptosis in tumour cells." (PMID 35242717, 2022). "Overexpression of TRAF4 in HCC tissues correlates with tumor number and vascular invasion." (PMID 35242717, 2022). "Nucleus TRAF4 expression is higher in HER-2/Neu cells than in basal cell types, suggesting that TRAF4 in the nucleus may play an essential role in tumour growth and invasion and may help guide the choice of chemotherapy regimens." (PMID 35242717, 2022). "HER2 and TRAF4 expression levels varied among these tumor tissues." (PMID 35864174, 2022). "HER2+ clusters mediate higher proliferative activity, and TRAF4 may be associated with HER2+, leading to more aggressive tumours." (PMID 35242717, 2022). "To investigate whether TRAF4 plays a role in tumor proliferation, we first performed IHC staining of TRAF4 and Ki67 in 32 tumor tissues from patients with NSCLC of phase IIIa." (PMID 35748027, 2022). "Next, we will further study how TRAF4 and Eg5 regulate the biological behavior of tumor cells." (PMID 35692762, 2022). "The results showed that TRAF4 knockout or suppression of MCL-1 with S63845 combined with radiotherapy could significantly inhibit tumor growth." (PMID 36535926, 2022). "We found that wogonoside could reduce the overexpression of TNF-α, TRAF2 and TRAF4 in later stage of tumor, and improved tumor microenvironment." (PMID 28774312, 2017). "We propose that TRAF4 in fibroblasts could be a potential target to sensitize tumor cells, and that radiotherapy combined with TRAF4 knockdown could be a promising strategy against NSCLC." (PMID 28827764, 2017). "Interestingly, one recent study also found that miR-4443 acts in a tumor-suppressive manner by down-regulating TRAF4, which further confirms our findings." (PMID 29163513, 2017). "Interestingly, both the lL‐8 neutralizing antibody and the CXCR1/2 inhibitor could hinder tumor sphere formation induced by TRAF4 nuclear accumulation." (PMID 39716976, 2025). "In addition, it has been reported that TRAF4 participates in regulating tumor microenvironment." (PMID 35692762, 2022). "However, according to our data, we propose that the overexpression of TRAF4 could be an essential feature of tumor cells, where an elevated TRAF4 expression induces activation of the EGFR‐TRAF4‐MEKK3‐ERK5 axis as the dominant pathway to promote tumorigenesis." (PMID 35748027, 2022). "TRAF4 produces cell-specific and diverse biological effects in the regulation of cell differentiation, polarity, proliferation, and apoptosis, affecting embryonic development, rule of reactive oxygen species production, and mediating tumor formation and evolution." (PMID 35242717, 2022).
tumor (continued). "However, obesity-induced leptin and/or insulin resistance could thwart such tumor-suppressing activity by miR-4443 on TRAF4/NCOA1 and lead to potentiating the risks for CRC clinical presentation in obese individuals." (PMID 31007685, 2019). "Furthermore, we investigated whether TRAF4/NOX complex-mediated endosomal ROS promotes secretion of soluble ICAM1 (sICAM1) to enhance tumor progression." (PMID 28827764, 2017). "Moreover, we showed that TRAF4 knockdown successfully delayed formation of tumor microenvironment." (PMID 28827764, 2017). "We found that TRAF4 enhanced tumor sphere formation and cell invasion in HCT116, MDA‐MB‐231, and U‐87 MG cells; conversely, TRAF4‐P12A suppressed these processes." (PMID 39716976, 2025). "To demonstrate the clinical relevance of our findings, we examined TRAF4, p-Akt, and survivin expression in NPC tumor tissues." (PMID 38164179, 2024). "In this study, we also confirmed TRAF4 as an accelerator of EGFR activation and its critical role in tumor genesis of NSCLC, as per the published data." (PMID 35748027, 2022). "MTO1 binds to TRAF4 as a competitive endogenous RNA (ceRNA) in MCF-7 and MDA-MB-231, leading to decreased Ki-67 expression, inhibiting tumor activity, and reversing chemotherapeutic drug resistance." (PMID 35242717, 2022). "In endometrial cancer, TRAF4 activates the PI3K/AKT signaling pathway and promotes tumor proliferation and migration." (PMID 35692762, 2022). "To support this finding, we treated TRAF4‐sufficient A549 xenograft models with an MEK5 inhibitor (Bix02189), which blocks ERK5 activation, and monitored tumor growth." (PMID 35748027, 2022). "Additionally, the mRNA level of Traf4 was positively correlated with two characteristic genes of cell proliferation, Cyclin D and C‐myc, suggesting that TRAF4 may play a critical role in tumor expansion." (PMID 35748027, 2022). "The qRT–PCR experiments indicated that TRAF4 and TRAF5 mRNA levels were relatively higher in the tumour tissues." (PMID 34983361, 2022). "Depletion of TRAF4 markedly improved the sensitivity of OSCC cells to irradiation (IR) treatment, showing that tumor cell proliferation, colony formation and xenograft tumor growth were reduced." (PMID 36535926, 2022). "Collectively, our data imply that the emergence of TRAF4 allows EGFR activation to engage the MEKK3‐ERK5 axis, promoting tumor formation through the induction of genes critical for cell proliferation." (PMID 35748027, 2022). "The expression of TRAF4 and MCL-1 were significantly upregulated in tumor tissues compared with that in paired adjacent non-tumor tissues." (PMID 36535926, 2022). "ZFPM2-AS1 is significantly upregulated in SCLC tissues and cells, and TRAF4 reverses ZFPM2-AS1 downregulation-mediated proliferation and invasion of SCLC cells in vitro and tumor function of growth." (PMID 35242717, 2022). "The present study found that TRAF4 was significantly upregulated in primary and relapsed OSCC tumor tissues." (PMID 36535926, 2022). "Recent reports suggest the N-terminal RING finger domain of TRAF4 has E3 ligase activity that ubiquitinates AKT, SMURF2, and TrkA to promote tumor growth and metastasis." (PMID 32357935, 2020). "TRAF4 overexpression reversed the suppressive function of ZFPM2-AS1 depletion on SCLC cell proliferation, invasion and migration in vitro as well as tumor growth in vivo." (PMID 32280300, 2020). "In the TRAF4-knockout HT29 tumors, reintroduction of WT TRAF4 impaired the anti-tumor effectiveness of the chemotherapeutic agents, but reintroduction of the DM-RING and C18A TRAF4 mutants, which both lack the E3 ligase activity, did not." (PMID 32357935, 2020). "Consistently, higher expression in tumor samples for two of the up-regulated genes (MAP2K1 and TRAF4) and lower expression in tumor samples for down-regulated genes (FAS) was observed to evidence their tumor specific regulation." (PMID 29254206, 2017).
tumor (continued). "Another group has shown that tumor-derived exosomal miR-494 and miR-542-3p were able to modify distant lymph nodes and lung tissue toward a pre-metastatic phenotype suitable for tumor cell hosting, by targeting cdh17 and MAL, and cdh17 and TRAF4, respectively." (PMID 26258125, 2015). "If the implanted tumor cells need to proliferate, TRAF4 will return to the cytoplasm and will not re‐enter the nucleus until it receives further stimulation from the microenvironment." (PMID 39716976, 2025). "Subsequently, the expression of TRAF4, c-Jun and Bcl-xL was examined in primary CRC tumor tissues." (PMID 36765039, 2023). "Overexpression of TRAF4, but not of TRAF4 C18A, restored the expression of Ki67 in tumor cells after radiotherapy." (PMID 36765039, 2023). "There was a positive correlation between TRAF4 and MCL-1 in primary and relapsed tumor samples." (PMID 36535926, 2022). "Moreover, TRAF4 was positively correlated with MCL-1 in primary and in radiotherapy-treated, relapsed tumor tissues." (PMID 36535926, 2022). "Comparison between the pairs of primary and recurrent tumor samples revealed that 5 genes were concordantly upregulated with a > twofold difference in expression level, including BCL10, BIRC3, CD40, TNFRSF10A and TRAF4." (PMID 34488754, 2021). "Our findings support the notion that TRAF4/6 mediates pro-tumorigenic effects of CD44, and suggests that inhibitors of CD44 signaling via TRAF4/6 and RAC1 may be beneficial in the treatment of tumor patients." (PMID 33804427, 2021). "Our results suggest that the inhibition of CD44 signaling via TRAF4 and RAC1 may be beneficial in tumor treatment." (PMID 33804427, 2021). "The expression of TRAF4 was significantly increased in tumor tissues when compared to paired adjacent non-cancerous tissues." (PMID 32357935, 2020). "A greater percentage of tissues exhibited positive TRAF4 or p-CHK1 staining when tumor tissues were compared to adjacent non-cancerous tissues." (PMID 32357935, 2020). "Finally, TRAF4 could countervail ZFPM2-AS1 downregulation-mediated function on SCLC cell proliferation and invasion in vitro and tumor growth in vivo." (PMID 32280300, 2020). "However, OA could not further prevent the metastasis and tumorigenesis in TRAF4‐KO cells, which indicated that OA inhibited tumor metastasis and initiation by targeting TRAF4." (PMID 39716976, 2025). "To illustrate the impact of TRAF4's nuclear translocation on tumor development, MMTV‐PyMT mice were utilized for our studies; we found that nuclear expression of TRAF4 was exclusively present in PyMT tumors and absent in normal mammary tissues." (PMID 39716976, 2025). "Conversely, TRAF2, TRAF4, and TRAF7 displayed positive correlations with stromal, immune, and estimated scores, and negative correlations with tumor purity." (PMID 38825674, 2024). "However, the downstream signaling pathway of TRAF4‐mediated EGFR activation, as well as its effects on tumor cells, have not been fully elucidated." (PMID 35748027, 2022). "Furthermore, when TRAF4 was knocked out, OA could no longer inhibit the expression of SOX2, Olig2, and MMP9, nor did it impair tumor sphere formation." (PMID 39716976, 2025).
infection (3 papers, 2016 to 2020). The state of being infected such as from the introduction of a foreign agent such as serum, vaccine, antigenic substance or organism. "From the same gene family, but after 6 h post-infection, the TRAF4 DEC shows the highest up-regulation by a fold change of 488.2 (Robust Exact Test, FDR = 1.04E− 3)." (PMID 33167855, 2020). "Six of these genes were predicted to be involved in host immune response to infection: PTN on BTA4, AP3B1 on BTA10, HSF1on BTA14, SHARPIN on BTA14, TRAF4 on BTA20 and FKBP5 on BTA23." (PMID 26960806, 2016).
brain diseases (1 paper, 2012). "Our findings show that TRAF4 is required for myelin integrity and Purkinje cell survival, and link the loss of TRAF4 function to brain diseases." (PMID 22363515, 2012).